LINC01694 (long independently transcribed non-coding RNA 1694)
Gene: Long non-coding RNA gene on chromosome 21 (45,590,717 to 45,603,088, forward strand). Ensembl gene ENSG00000233922.
Diseases named in the same sentence as LINC01694 in open-access papers:
LINC01694 is named in the same sentence as 1 disease in open-access papers, as found by Europe PMC text mining. Sharing a sentence is not in itself a finding about the gene and the disease. The quoted sentences say what the papers report.
tumor (2 papers, 2020 to 2025). "RNA sequencing indicates that NSUN5P2, Linc01694, and DLC1 in differential genes are associated with the cell cycle and the enhancement or inhibition of tumor cell proliferation and invasion, respectively." (PMID 40708858, 2025). "Nude mouse xenograft models revealed that in nude mice injected with cells transfected with HBLV-h-LINC01694, the tumor volume and mass increased significantly, miR-340-5p decreased, and the relative expression of Sox4 mRNA and protein increased." (PMID 32270853, 2020). "In GSE74048 chip, the elevated expression of LINC01694 in tumor samples was revealed." (PMID 32270853, 2020).